FAS (Fas cell surface death receptor)
Diseases named in the same sentence as FAS in open-access papers (continued):
Sharing a sentence is not in itself a finding about the gene and the disease.
Alzheimer disease (8 papers, 2012 to 2026). A progressive, neurodegenerative disease characterized by loss of function and death of nerve cells in several areas of the brain leading to loss of cognitive function such as memory and language. "Several studies have found the expression of FAS in plasma, gray matter, and white matter is significantly enhanced in Alzheimer's disease (AD) patients." (PMID 35237223, 2021). "Fifteen of the altered proteins mapped to 12 different pathways: pathological pathways included Apoptosis signaling pathway (P00006, FASL, Granzyme B), FAS signaling pathway (P00020, FASL) and Alzheimer disease-presenilin pathway (P00004, E-Cadherin)." (PMID 32804078, 2020). "Ten different proteins mapped to 12 different pathways: Apoptosis signaling pathway (P00006, FASL, Trail), FAS signaling pathway (P00020, FASL) and Alzheimer disease-presenilin pathway (P00004, E-Cadherin)." (PMID 32804078, 2020). "Fourteen different proteins mapped to 11 different pathways, pathological pathways include: Apoptosis signaling pathway (P00006, TNF-R2, FASL, Granzyme B) and FAS signaling pathway (P00020, FASL) and Alzheimer disease-presenilin pathway (P00004, E-Cadherin)." (PMID 32804078, 2020). "Potentially, pathological pathways included Apoptosis signaling pathway (P00006, FASL), FAS signaling pathway (P00020, FASL) and Alzheimer disease-presenilin pathway (P00004, MPP-2)." (PMID 32804078, 2020). "Thirteen different proteins mapped to 12 different pathways, pathological pathways were: Apoptosis signaling pathway (P00006, FASL), FAS signaling pathway (P00020, FASL) and Alzheimer disease-presenilin pathway (P00004, E-Cadherin)." (PMID 32804078, 2020). "Although most of the genes were involved in several of these pathways, some of them were restricted to Huntington’s disease (AP2B1, CREB3L4, POLR2H and SOD1), to Alzheimer ́s disease (NAE1, FAS) or to Parkinson’s disease (PARK7)." (PMID 24742402, 2014). "Twelve different proteins significantly altered by 48 hr after mTBI mapped to 11 different functional pathways, pathological pathways were: Apoptosis signaling pathway (P00006, FASL, TNF-R2), FAS signaling pathway (P00020, FASL) and Alzheimer disease-presenilin pathway (P00004, E-Cadherin, MMP-9)." (PMID 32804078, 2020). "Enhanced FAS and FASL expression levels in brain cells accompany neurodegenerative and neurological disorders’ onsets, i.e., during experimental autoimmune encephalomyelitis (EAE model), exposure to heavy metals (e.g., cadmium), as well as in Alzheimer’s disease." (PMID 39771121, 2024).
B cell lymphoma (8 papers, 2011 to 2025). "E.g., a genome-wide CRISPR/Cas9 screen identified the necessary role for FAS/FASLG in CD19-directed CAR T cell killing in an in vivo model of B cell lymphoma." (PMID 39843653, 2025). "Besides, nucleoin was supposed to bind FAS, block the FAS/FASL interaction, and thus inhibit the FAS-mediated apoptosis in B-cell lymphoma." (PMID 34319045, 2021).
Cirrhosis (8 papers, 2012 to 2021). A chronic disorder of the liver in which liver tissue becomes scarred and is partially replaced by regenerative nodules and fibrotic tissue resulting in loss of liver function. "In the other hand, for group 4, we observed a decrease in FAS expression in PBMCs, and this was significantly associated with cirrhosis and intense necroinflammation." (PMID 23256595, 2012). "For example some genes, such as FAS, had only studies relating to cirrhosis and/or fibrosis." (PMID 29397014, 2018). "The increase in the mRNA expression of FAS and FASL was correlated with higher levels of inflammation and disease progression, followed by a decline in tissues with cirrhosis, and it was also associated with increased levels of alanine aminotransferase (ALT) and aspartate aminotransferase (AST)." (PMID 27243827, 2016).
colorectal tumor (8 papers, 2010 to 2024). "A key feature of human colorectal tumor is loss of FAS expression." (PMID 35053524, 2022). "Knockout or inhibition of PIR dramatically increases FAS expression, FAS‐dependent apoptosis and attenuates colorectal tumor formation in mice." (PMID 38148593, 2024). "FAS expression has been documented in colorectal tumors, simultaneously to increase fatty acid synthesis." (PMID 38474695, 2024). "The FAS promoter DNA is hypermethylated in these three CpG sites in human colorectal tumors as compared to normal colon tissue." (PMID 35053524, 2022). "Analysis of FAS expression level in different stages of human colorectal tumors indicated that FAS expression decreases with tumor progression, and the lowest FAS expression is in stage IV colorectal tumors." (PMID 35053524, 2022). "It has been shown that the interaction between FAS and its ligand (FAS-L) induced FAS-positive cell apoptosis in colorectal tumor cell lines." (PMID 20205946, 2010). "We aimed at determining whether restoring FAS expression is sufficient to suppress colorectal tumor growth." (PMID 35053524, 2022). "Normal colon tissues share similar FAS expression cellular patterns as colorectal tumor cells." (PMID 35053524, 2022). "The FAS expression level is lower in colorectal tumor cells." (PMID 35053524, 2022). "However, it is unknown whether restoring FAS expression alone is sufficient to suppress metastatic colorectal tumors." (PMID 35053524, 2022).
endometriosis (8 papers, 2016 to 2025). The growth of functional endometrial tissue in anatomic sites outside the uterine body. "The results indicate a positive association between the rs3740286 and rs4064 of the FAS gene and the risk of developing endometriosis." (PMID 30036894, 2018). "The results indicate an association between FAS gene polymorphisms and the risk of developing endometriosis." (PMID 30036894, 2018). "Regarding the two FAS SNPs, our results suggest a significant effect on the susceptibility to endometriosis." (PMID 30036894, 2018). "Regarding the polymorphism FAS rs4064 (C ˃ G), there was an association between the genotypes of the polymorphism studied and the development of endometriosis (χ2 = 6.48; p = 0.039)." (PMID 30036894, 2018). "For polymorphism FAS rs3740286 (A ˃ G), the association between the genotypes of the polymorphism and the development of endometriosis was observed (χ2 = 8.52; p = 0.014)." (PMID 30036894, 2018). "Interestingly, they found a positive association between polymorphisms of the Fas cell surface death receptor gene FAS and the confirmed surgical diagnosis of endometriosis." (PMID 30352469, 2018). "Therefore, the present study aims to investigate the association between CASP8 (rs13416436 and rs2037815) and FAS (rs3740286 and rs4064) polymorphisms with endometriosis in Brazilian women." (PMID 30036894, 2018). "Genome-wide association studies have reported a significant association of endometriosis with chromosomes 2 and 10, which harbor CASP8 and FAS genes respectively." (PMID 30036894, 2018). "We read with great interest the article by Pissetti et al1 entitled ‘Gene Polymorphisms in FAS (Rs3740286 and Rs4064) Are Involved in Endometriosis Development in Brazilian Women, but not those in CASP8 (rs13416436 and rs2037815),’ published in your journal." (PMID 30352469, 2018). "Single nucleotide polymorphisms (SNPs) in apoptotic genes, such as those of the Fas cell surface death receptor (FAS) and the caspase-8 (CASP8) genes, may be involved with the development of endometriosis." (PMID 30036894, 2018).
Hyperglycemia (8 papers, 2013 to 2025). An increased concentration of glucose in the blood. "However, due to other pro-lipogenic factors induced by hyperglycemia, the overall lipogenic gene (FAS) in STZ- treated mice was still increased." (PMID 33186123, 2020).
liver fibrosis (8 papers, 2013 to 2025). "In addition, liver lipid synthesis markers (FAS) and hepatic fibrosis markers (such as TGF‐ꞵ, α‐SMA, and MMP2) were increased in the WD‐treated group, but these elevations were significantly decreased by the oral administration of both PNVs and EA." (PMID 40212474, 2025). "Taken together, our results show that let-7 is effective in mitigating CCl4-induced liver fibrosis likely by simultaneously targeting the TET3/TGF-β and the FAS-mediated pathways in hepatocytes." (PMID 37898449, 2023). "FAS-mediated apoptosis of hepatocytes and aberrant TGF-β signaling are major drivers of liver fibrosis." (PMID 37898449, 2023). "Thus, let-7 significantly mitigates liver fibrosis in the BDL model likely by simultaneously targeting the TET3/TGF-β and the FAS-mediated pathways in hepatocytes." (PMID 37898449, 2023).
lung adenocarcinoma (8 papers, 2017 to 2024). A carcinoma that arises from the lung and is characterized by the presence of malignant glandular epithelial cells. "We found that the expression of FAS was significantly downregulated in both lung adenocarcinoma (LUAD) and lung squamous cell carcinoma (LUSC) compared to normal lung tissue." (PMID 39416461, 2024). "FAS/CD95, is an important suppressor as apoptosis inductor and often downregulated in lung adenocarcinoma cells." (PMID 31192122, 2019). "In this study, we found that the expression of FAS was associated with better OS in lung adenocarcinoma but not in lung squamous cell carcinoma." (PMID 31942177, 2020). "TCGA lung adenocarcinoma (ADC) (n = 469) samples and lung SCC (n = 378) samples having both miR-196b-5p and FAS expression data available were selected for Pearson correlation analysis." (PMID 32963220, 2020). "It is still unknown why FAS only has a prognostic value in lung adenocarcinoma patients but not in lung squamous cell carcinoma patients." (PMID 31942177, 2020).
neuroblastoma (8 papers, 2010 to 2021). Neuroblastoma (NB) is the most common solid, extracranial childhood tumor. "It was observed that significantly increased risks of neuroblastoma associated with FAS -1377G/A and FASL -844T/C polymorphisms, with ORs equal to 1.55 (95% CI, 1.10–2.20) for FAS -1377 A allele and 2.90 (95% CI, 2.04–4.12) for FASL -844CC genotype carriers compared with non-carriers, respectively." (PMID 23951214, 2013). "In addition, the cumulative effect of FAS and FASL polymorphisms on risk of neuroblastoma was observed (P for trend = 2.502×10−10), with OR for the carriers of both FAS -1377A allele and FASL -844CC genotypes equaled to 3.95 (95% CI, 2.40–6.51)." (PMID 23951214, 2013). "Risk of neuroblastoma associated with the FAS -1377G/A genotypes by FASL -844T/C genotypes." (PMID 23951214, 2013). "We showed that KDM1A inhibition in IMR-5/75 neuroblastoma cells induced FAS cell surface expression to higher levels than irradiation in a direct comparison." (PMID 34771652, 2021). "FAS upregulation sensitized neuroblastoma cells to FAS-FASL-dependent death, and enabled L1CAM-directed CAR T cells to eradicate antigen-negative tumor cells in vitro." (PMID 34771652, 2021). "To test the functional significance of FAS induction on neuroblastoma cells for CAR T cell efficacy, we combined SP-2509 and L1CAM-specific CAR T cell treatments in vitro." (PMID 34771652, 2021). "FAS expression on the neuroblastoma cell surface was flow cytometrically assessed after 24 h of IFNG treatment." (PMID 34771652, 2021). "FAS upregulation sensitized neuroblastoma cells to FAS-FASL-dependent killing and augmented L1CAM-directed CAR T cell therapy against antigen-poor or even antigen-negative tumor cells in vitro." (PMID 34771652, 2021). "FAS upregulation sensitized neuroblastoma cells to death via the FAS-FASL axis and enabled L1CAM-directed CAR T cells to eradicate antigen-negative tumor cells in vitro." (PMID 34771652, 2021). "We inhibited KDM1A in the childhood tumor, neuroblastoma, to increase FAS expression on tumor cells." (PMID 34771652, 2021). "We next examined the consequence of inhibiting Drp1/Fis1 interaction in another model of AD disease, neuroblastoma cells expressing a mutant form of APP, a mutation that is associated with FAS, found in a Swedish family (KM670/671NL)." (PMID 29464060, 2018). "Genotype and allele frequencies of FAS and FASL among cases and controls, and their contributions to risk of neuroblastoma." (PMID 23951214, 2013). "We tested whether IFNG treatment could upregulate FAS expression on our selected neuroblastoma cell lines." (PMID 34771652, 2021). "Interestingly, an IFNG-mediated increase in FAS expression only occurred in NB-1 neuroblastoma cells, which already expressed high FAS levels before IFNG treatment." (PMID 34771652, 2021). "Indeed, we observed FAS upregulation in neuroblastoma cells, but only in the presence of very high IFNG concentrations, which would be unrealistic in an in vivo setting." (PMID 34771652, 2021).
neuroblastoma (continued). "This work reveals that polymorphisms of FAS -1377G/A and FASL -844T/C but not FAS -670A/G are associated with risk of neuroblastoma in Chinese." (PMID 23951214, 2013). "Moreover, a cumulative effect of FAS -1377G/A and FASL -844T/C polymorphisms on risk of neuroblastoma was also observed." (PMID 23951214, 2013). "This pathway might remain inactive, however, since FAS expression is downregulated on cells in a number of tumors, including gastric, colon, thyroid, and small cell lung carcinomas, consistent with our observations in neuroblastomas." (PMID 34771652, 2021). "The other two neuroblastoma cell lines, with the lower levels of L1CAM target expression, exhibited only very low FAS levels on the cell surface that were only slightly upregulated by IFNG treatment regardless of concentration." (PMID 34771652, 2021). "Analysis of public RNA-sequencing data from primary neuroblastomas revealed that a particular epigenetic modifier, the histone lysine demethylase 1A (KDM1A), correlated negatively with FAS expression." (PMID 34771652, 2021). "Pearson correlation analysis in two independent neuroblastoma cohorts consisting of 47 and 51 tumor samples demonstrated that KDM1A and FAS expression were negatively correlated." (PMID 34771652, 2021). "Therefore, we aimed to epigenetically increase FAS levels on neuroblastoma cells to unleash this antigen-independent killing pathway and improve CAR T cell efficacy against neuroblastomas with heterogeneous or low target antigen expression." (PMID 34771652, 2021). "We did not observe FAS upregulation on neuroblastoma cells after exposure to IFNG concentrations equivalent to those produced by T cells upon in vitro tumor cell encounter." (PMID 34771652, 2021). "We next explored whether FAS upregulation by KDM1A inhibition was sufficient to kill even antigen-negative neuroblastoma cells via the FAS-FASL axis." (PMID 34771652, 2021). "Blockade of FAS activity in the neuroblastoma cells eliminated the increase in tumor cell lysis observed in cells pretreated with the KDM1A inhibitor but did not impact CAR T cell-directed killing of untreated neuroblastoma cells." (PMID 34771652, 2021). "Combining the inhibitor, SP-2509, with neuroblastoma-specific CAR T cells improved their efficacy, especially against neuroblastoma cells with low levels of tumor antigen, where insufficient upregulation of FAS by T cell-produced proinflammatory cytokines was observed." (PMID 34771652, 2021). "FAS upregulation via KDM1A inhibition sensitized neuroblastoma cells to FAS-FASL-mediated killing and augmented CAR T cell therapy against antigen-poor or even antigen-negative neuroblastoma." (PMID 34771652, 2021).
triple-negative breast carcinoma (8 papers, 2021 to 2025). An invasive breast carcinoma which is negative for expression of estrogen receptor (ER), progesterone receptor (PR), and human epidermal growth factor receptor 2 (HER2). "Triple-negative breast cancer (TNBC) cells are often resistant to FAS (CD95)-mediated apoptosis, but the underlying molecular mechanism(s) is not fully understood yet." (PMID 39056676, 2024). "Recent studies have also indicated the involvement of FAS/CD95 expression in the control of inflammatory signaling pathways in triple-negative breast cancer (TNBC)." (PMID 37667281, 2023).
lipid metabolism disorders (7 papers, 2014 to 2025). "It has been reported that SREBP-1 is an important factor regulating lipid metabolism disorder and is tangled in the regulation of lipid breakdown of key enzymes such as FAS to catalyze the synthesis of long-chain fatty acids." (PMID 32714403, 2020). "In agreement with previous studies, our study also showed that VOdipic-Cl improves liver lipid metabolism disorders by down-regulating the expression of PPARγ, C/EBPa, SREBP-1c and FAS proteins related to lipid synthesis." (PMID 35739990, 2022). "Previous studies have shown that HNK can alleviate lipid metabolism disorders of NASH by suppressing the expression of SREBP-1c, FAS, SCD-1 and promoting the phosphorylation of ACC, which are the key genes involved in fatty acid and unsaturated fatty acid biosynthesis pathways." (PMID 37709801, 2023).
Lymphadenopathy (7 papers, 2009 to 2025). Enlargement (swelling) of a lymph node. "A typical presentation of ALPS with the characteristic lymphadenopathy and a demonstrated FAS mutation is illustrated by Case LYWS-042 submitted by C. Chen from an 8-year-old boy with extensive lymphadenopathy." (PMID 40748381, 2025). "ALPS is a genetic disorder of FAS apoptotic pathway causing autoimmune cytopenia, organomegaly, lymphadenopathy and increased risk of malignancy." (PMID 24460868, 2014).
multiple myeloma (7 papers, 2009 to 2021). "For example, IL-1β, IL-6, IL-10, IFN-α, IGF-1 and TGF-γ promote proliferation of multiple myeloma cells, whereas IFN-β1 and APO-1/FAS inhibit the growth of multiple myeloma cells." (PMID 22792345, 2012). "CXCL10 activates CXCR3A receptors on myeloma cells, which attenuated apoptosis mediated by FAS (CD95)." (PMID 28176846, 2017).